PPARA (peroxisome proliferator activated receptor alpha)
Diseases named in the same sentence as PPARA in open-access papers (continued):
Sharing a sentence is not in itself a finding about the gene and the disease.
diabetes (continued). "Clinical trials have only shown modest effects of PPARα (fibrates) and PPARγ (thiazolidinediones and pioglitazone) agonists in reversing ART lipoatrophy, while other studies suggested these drugs may be useful in treating ART-associated diabetes and NAFLD." (PMID 23641933, 2013). "Therefore, both clinical observations and rodent experiments suggest that PPARα activation may play a beneficial role in diabetes induced nephropathy." (PMID 21076544, 2010). "Moreover, PPARα-null mice showed higher neonatal mortality than wild-type mice: for mice without diabetes, the rate was13.3% versus 5.1%, respectively, and for mice with diabetes, 78.9% versus 27.7%." (PMID 18401459, 2008). "We therefore investigated the association between PPARA gene variation with risk of CVD and diabetes related traits in Caucasian subjects with type 2 diabetes participating in the prospective population-based Genetics of Diabetes Audit and Research in Tayside Scotland (Go-DARTS) study." (PMID 16309557, 2005). "Farnesoid X receptor (FXR), liver X receptor (LXR), peroxisome proliferator-activated receptor α (PPARα), retinoid acid receptor-related orphan receptor γ (RORγ), and pregnane X receptor (PXR) are of great significance to diabetes." (PMID 40650120, 2025). "This conception is supported by previously published experimental data showing that overexpression of PPARα leads to lipid accumulation and the development of DCM, and that pharmacological inhibition of PPARα reduces cardiac lipotoxicity in diabetes." (PMID 37215098, 2023). "The recent Pemafibrate to Reduce Cardiovascular Outcomes by Reducing Triglycerides in Patients with Diabetes (PROMINENT) trial for Pemafibrate - a highly active and selective PPARα agonist - in diabetic patients was stopped in April 2022." (PMID 36768666, 2023). "To explore the role of PPARα in diabetic corneal wound healing, we fed STZ-induced diabetic (STZ-DM) C57BL/6J mice with fenofibrate chow for 3 mo starting at the diabetes onset." (PMID 36943878, 2023). "Some potent and selective PPARα modulators (SPPARMs), such as K-877, GW9578, and elafibranor, are currently under development for the treatment of NAFLD and diabetes, respectively." (PMID 36589809, 2022). "Studies of renal function in a genetic model of diabetes (db/db) show AMPK and PPARa engagement by AdipoRon and have revealed changes in lipid parameters in response to AdipoRon in renal endothelial cells." (PMID 35297761, 2022). "GCG, IRS1, VEGFA, STAT3, CCL2, CASP3, and APOE as diabetes mellitus-related proteins and SREBF1, LPL, PPARA, APOB, GPT, MAPK8, and FASN as NAFLD-specific proteins were identified as possible discriminating factors between the two studied diseases." (PMID 35154608, 2021). "To assess the effects of PPARα ablation on retinal neurodegeneration, we utilized the STZ mouse model, which develops subtle neurodegeneration in long-term diabetes." (PMID 30716067, 2019). "Interestingly, PPARα is downregulated in the diabetic retina and kidney, and although the regulatory mechanisms responsible for diabetes-induced PPARα downregulation are unclear, decreased PPARα levels may play a pathological role in diabetic microvascular complications." (PMID 25705219, 2015). "These present studies also identify MuRF2 as the first ubiquitin ligase to regulate cardiac PPARα and PPARγ1 activities in vivo via post-translational modification without degradation and may represent a novel potential therapeutic target against heart failure in diabetes." (PMID 26242235, 2015). "Our results are consistent with the reports of previous studies that the expression of PPARα, VDR, and FXR was downregulated by the induction of diabetes." (PMID 24465611, 2014). "Animal models of diabetes and obesity, including STZ-induced diabetic rats, db/db mice, and ob/ob mice, show increased cardiac PPARα activation." (PMID 20838448, 2010).
diabetes (continued). "In contrast, cardioprotective effects of FF reported for young animals in pathological models of hypertension, myocardial ischemia followed by reperfusion injury, and diabetes have been attributed in part to its ability to enhance mitochondrial function and promote FAO through PPARα activation." (PMID 40869358, 2025). "After many years of fenofibrate application in cardiovascular disorders and in type 2 diabetes mellitus (T2DM), it is time to consider the application of PPARα agonist(s) in AD and other neurodegenerative disorders, particularly in the cases of patients with altered lipid metabolism." (PMID 39000217, 2024). "Even without diabetes, global PPARα knockout mice and corneal epithelium-specific PPARα conditional knockout mice showed disturbed mitochondrial function and delayed wound healing in the cornea, similar to that in diabetic corneas." (PMID 36943878, 2023). "In addition to its antilipidemic actions, FE acts as a peroxisome proliferator-activated receptor alpha (PPARα) agonist that has been reported to prevent the progression of DR and AMD in patients with diabetes." (PMID 35897940, 2022). "The mRNA concentrations of PPARγ and GLUT-4 (two proteins documented as key diabetes targets) were increased by 3T3-L1 adipocytes treated with compounds 1–4, but an absence of in vitro expression of PPARα was observed." (PMID 35056159, 2022). "Some studies point that PPARα expression is downregulated during diabetes, mediated by not only transcriptional regulation but also posttranslational modification." (PMID 36589809, 2022). "YQ could attenuate type 2 diabetes mellitus by improving ß-cell via IRS-2/AKT/GLUT4 pathway and NAFLD by ameliorating lipid accumulation via AMPKα/ACC1/PPARα/SREBP1 pathway." (PMID 34621322, 2021). "YQ could attenuate type 2 diabetes mellitus by improving islet α- and ß-cells via IRS-2/AKT/GLUT4 pathway and nonalcoholic fatty liver by ameliorating lipid accumulation via AMPK/PPARα/SREBP1/ACC1 pathway." (PMID 34621322, 2021). "Considering that T2D is by far the most common type of diabetes, in this review, we focus on evidence behind DCM in T2D to discuss the roles of PPARα not only in energy metabolism but also in insulin resistance, oxidative stress, inflammation, and Ca2+ handling regulation." (PMID 33397369, 2021). "Especially, a decrease in cardiac PPARα 39, 40 and an increase in CPT1 are observed in STZ‐induced diabetes, suggesting that there exist other unknown signalling pathways in the regulation of CPT1 expression in diabetic hearts." (PMID 32450616, 2020). "To evaluate potential in vivo antioxidant effects of PPARα, we used a quantitative multiplex proteomics approach to measure retinal levels of antioxidant enzymes in wild-type and Pparα-/- mice with STZ-induced diabetes." (PMID 30716067, 2019). "The PPARα agonist fibrates decrease fetuin-A expression in obese patients with or without type 2 diabetes mellitus." (PMID 28781590, 2017). "Further, our group found that retinal levels of PPARα, but not PPARγ or PPARβ/δ, were decreased in diabetes, suggesting that PPARα plays a more crucial role than other PPARs in repressing development of diabetic retinopathy (DR)." (PMID 25705219, 2015). "Pdk4 was also induced in rat gastrocnemius muscle after treatment of the animals with the PPARα agonist WY14643, by streptozotocin-induced diabetes, or by starvation, i.e. conditions where increased levels of long-chain fatty acids may activate PPARα." (PMID 20847941, 2010). "More recently,evidence for a key role of PPARα in placenta development was demonstrated by increasedabortion rate (by 20%) in PPARα-null mice without diabetes." (PMID 18401459, 2008). "However, sex differences related to PPARγ have been observed in human T cells, alongside changes in the expression of PPARα, and in fetal mice in nutritional programming studies and parental diabetes with no change in PPARα." (PMID 40829644, 2025).
diabetes (continued). "Similarly, IPA for “canonical pathways” identified pattern recognition, apelin cardiomyocyte signaling, white adipose tissue browning, SNARE signaling, complement system, PPARα, RxR α activation, IL-8 signaling, NAD homeostasis and CLEAR signaling as enriched in diabetes." (PMID 36902363, 2023). "Importantly, microglial density was increased in global Pparα−/− mice without diabetes." (PMID 36497130, 2022). "However, PPARA genotype correlated with 5-year mortality in diabetic (22.2% AA vs. 18.8% AG vs. 39.5% GG; P = 0.008), but not non-diabetic (P = 0.96) subjects (genotype by diabetes interaction P = 0.008)." (PMID 20838448, 2010). "The PPARα 162Val allele was nearly associated with higher HDL levels at univariate (46.1 ± 14 vs. 43 ± 10 mg/dl, p = 0.051), but not at multivariate analysis, and patients positive for this allele had a trend for a higher prevalence of diabetes/IFG compared to those without (25% vs. 16%; p = 0.06)." (PMID 20825652, 2010). "Furthermore, it has been shown that a PPARα agonist stimulated corneal nerve regeneration in patients with T2DM and protected the corneal nerve from degeneration in a mouse model of diabetes, suggesting that the use of the PPARα agonist may be promising strategy for treating DPN." (PMID 40917479, 2025). "A further interrogation indicated that the levels of transcriptional regulator PPARα and key enzyme carnitine palmitoyltransferase-1α (CPT1α) related to FAO were markedly lower in diabetic individuals compared with samples obtained from people without diabetes." (PMID 32444604, 2020).
steatosis (335 papers, 2005 to 2026). Increased lipid within the cytoplasm of cells. "In murine models with PPARA deficiency, it is demonstrated that this factor is crucial for lipid storage and energy homeostasis, leading to steatosis." (PMID 41373582, 2025). "In palmitate-induced steatosis, allicin was associated with PPAR signaling nodes and confirmed by qPCR to up-regulate PPARA and FABP6 while down-regulating FABP4 and PPARG, demonstrating a compound-target-pathway framework anchored in the mechanism." (PMID 41305007, 2025). "Mice with hepatic PPARα deficiency exhibited more severe liver inflammation and steatosis when fed HFD." (PMID 38397045, 2024). "The authors demonstrated that PFAS induced triglyceride accumulation and altered the expression of genes associated with steatosis, PPARα target genes, and genes related to lipid and cholesterol metabolism." (PMID 39596398, 2024). "Research findings indicate that DLPCB causes steatosis through the up-regulation of PPARγ, which leads to an increase in lipid accumulation, and the down-regulation of PPARα, which decreases fatty acid oxidation." (PMID 38779445, 2024). "The liver PPARα expression was negatively associated with severity of steatosis, NASH, and fibrosis." (PMID 37673856, 2023). "Treatment with a PPARα agonist has been shown to protect wild-type mice from steatohepatitis and steatosis when given a methionine-choline-deficient (MCD) diet." (PMID 38034083, 2023). "Studies in mice show that the loss of PPARα in the liver results in simple steatosis on a normal chow diet, which is worsened on a high-fat diet." (PMID 36148775, 2022). "In this study, the prevention of dexamethasone-induced steatosis was associated with a restoration of hepatic PPARα expression." (PMID 35162986, 2022). "Cardiac-specific ABHD5 deficiency leads to steatosis and heart failure through the inhibition of lipolysis and PPARα-dependent FA oxidation, which provokes endoplasmic reticulum stress and mitochondrial dysfunction." (PMID 36230994, 2022). "PPARα and PPARγ were also shown to be associated with steatosis and the antioxidant response, and exhibited decreased and increased protein levels, respectively, concomitant with liver damage severity in patients with WD." (PMID 34098115, 2021). "Hepatic miR-34a overexpression was observed in NAFLD, and miR-34a upregulation caused steatosis by downregulating peroxisome proliferator-activated receptor alpha (PPARα) and sirtuin 1 (SIRT1)." (PMID 35052597, 2021). "Rodents on methionine-choline deficient diet developed moderate steatosis, while PPARα knockout provokes a severe NASH unaffected by its agonist (Wy14643) administration." (PMID 33926085, 2021). "PPARα deficiency results in severe steatosis and hepatitis, whereas treatment with the PPARα agonist Wy-14,643 protects against steatosis and steatohepatitis in methionine- and choline-deficient diet-fed mice." (PMID 34285335, 2021). "The mechanisms involved in the susceptibility to steatosis and protection from glucose intolerance likely involve the well-established role of PPARα in the control of fatty acid transport and degradation." (PMID 32300166, 2020). "Recent studies have shown that PPARα and PPARγ are associated with steatosis and impairment of the antioxidant system in the liver of WD patients." (PMID 32485807, 2020). "Ablation of PPARα has been shown to be associated with elevated hepatic triglycerides, cholesterol esters, and steatosis." (PMID 33104749, 2020). "Recent studies showed that activation of PPARγ induces hepatic steatosis, and that lipid accumulation is exhibited in PPARα-deficient mice." (PMID 30298052, 2018). "Resulting from circRNA_0046367 deficiency and miR-34a activation, PPARα inhibition represented one of the most important characteristics of groups with FFA-induced steatosis." (PMID 29018509, 2017). "PPARα-null mice have provided valuable clues regarding the role of PPARα in energy balance in the liver and susceptibility to steatosis." (PMID 25689681, 2015).
steatosis (continued). "However, several human studies found that the clinically used PPARα agonists have very limited effects in improving MAFLD-associated steatosis." (PMID 40981382, 2025). "Indeed, in our HepG2 cell model of steatosis, the lipotoxic effect of OA stimulation was found to be associated with downregulation of PPARα and upregulation of CYP2E1 proteins." (PMID 38474427, 2024). "Studies have shown that hepatic deficiency in PPARα can impair the ability of the liver to utilize fatty acids, resulting in lipid deposition, whereas its activation can enhance the expression of fatty acid oxidation genes and reduce steatosis." (PMID 37188264, 2023). "Some studies have shown that PPARα deficiency in the liver impairs the ability of the organ to utilize fatty acids, resulting in lipid deposition, whereas PPARα activation enhances the expression of genes related to fatty acid oxidation and reduces steatosis." (PMID 37188264, 2023). "A disordered GM may inhibit the expression of peroxisome proliferator-activated receptor alpha (PPARα) and thereby inhibit the genes associated with lipid decomposition, further leading to steatosis." (PMID 35873168, 2022). "Hepatic Hif1α deletion in a mouse model of NAFLD (mice fed a choline deficient diet), however, led to lower Lipin1 mediated PPARα/PGC1α pathway activation, which worsened steatosis relative to wild type mice, suggesting HIF1α is required to maintain FAO in NAFLD." (PMID 34692739, 2021). "Furthermore, circRNA_0046367 expression was subjected to normalization in HepG2 cells with high-fat-induced steatosis, exhibiting its effect on miR-34a/PPARα regulatory system and downstream genes associated with lipid metabolism." (PMID 29018509, 2017). "Interestingly, in a previous study it was found that Pparα and Pparγ occupied more chromatin binding sites in the livers of 21 month-old mice affecting the lipid metabolism and causing steatosis." (PMID 28068403, 2017). "PPARα-null mice are highly susceptible to fasting-induced steatosis and hyperlipidemia." (PMID 25689681, 2015). "A subset of the high fat diets caused PPARα suppression presumably, because steatosis had progressed to steatohepatitis, although this hypothesis needs to be confirmed independently." (PMID 25689681, 2015). "PPARα-deficient mice develop hypertriglyceridemia and fasting-induced steatosis." (PMID 25141153, 2014). "Indeed, compound homozygous PPARα−/−, Acox1−/− mice lack increased peroxisomal proliferation and exhibit reduced steatosis and liver cell proliferation, thus verifying the essential role of PPARα in the pathogenesis of Acox1-deficient mice." (PMID 21760938, 2011). "Besides, the choline-deficient high-cholesterol diet (CDHCD) model (1–2% cholesterol) induced hepatic cholesterol overload and steatosis within 4–12 weeks, yet its metabolic relevance was limited by paradoxical weight loss and suppressed PPARα-mediated lipid oxidation." (PMID 40221799, 2025). "PPARα is a crucial regulatory element of fatty acid oxidation in the liver, and its activation can enhance inflammation, steatosis, and fibrosis in non‐alcoholic fatty liver disease." (PMID 40697704, 2025). "PPARα activation significantly reduced steatosis in both WT and Tg mice, and only enlarged hepatocytes and some residual steatosis around the portal triad area were observed after WY administration." (PMID 40815899, 2025). "The study demonstrated that Pac inhibited the MAPKs signaling pathway and reduced hepatic ferroptosis, alleviated steatosis through PPARα regulation, offering a potential therapeutic strategy for MASLD." (PMID 40395733, 2025). "PPARA-mediated fatty acid β-oxidation (FAO) was drastically inhibited in Alb/AEG-1 mice, thus causing steatosis, and was augmented in AEG-1ΔHEP mice thus providing protection from developing HFD-induced steatosis." (PMID 40282551, 2025).